SMAD4 (SMAD family member 4)
Diseases named in the same sentence as SMAD4 in open-access papers (continued):
Sharing a sentence is not in itself a finding about the gene and the disease.
tumor (continued). "In the later stages of tumorigenesis, tumor-promoting effects of stromal TGFβ signaling can occur independently of epithelial cancer cells, in which TGFβ pathway components, such as SMAD4 and TGFΒR2, are often mutationally inactivated." (PMID 38731846, 2024). "Previous study has reported that loss‐of‐function alterations in SMAD4 result in TGF‐β being a tumor‐promoting pathway through its interaction with other proteins." (PMID 38230565, 2024). "Typically, TGF-β regulates epithelial cell growth, and mutations in TGF-β signaling molecules, such as TGF-βRII and SMAD4, are associated with tumor formation in the gastrointestinal tract." (PMID 39404428, 2024). "In contrast, the loss or dysfunction of the SMAD4 gene promotes tumor initiation and progression through various mechanisms." (PMID 39164192, 2024). "Alterations in SMAD4, including downregulation or loss of protein expression, are associated with increased tumor and metastatic ability, and these changes are often closely associated with poor prognosis in CRC patients." (PMID 39164192, 2024). "Mutational status of BRAF, RAS, and SMAD4 in tumor tissue from mCRC patients candidate for liver metastasectomy should be considered to select those patients with a higher chance of benefiting from the surgical treatment." (PMID 39220128, 2024). "Univariate analysis links loss of DPC4/Smad4 to poor prognosis, but multivariate analysis reveals dependence on tumor size and lymph node involvement." (PMID 38666907, 2024). "According to this model, the loss of Smad4 converts Sox4 from an inducer of apoptosis to a TGF-β1 tumor promoter." (PMID 38675493, 2024). "SMAD4 deficiency increases tumor cell immunogenicity by enhancing spontaneous DNA damage and boosting sting-mediated type I interferon signaling." (PMID 38215117, 2024). "Studies using animal models of metastatic lung cancer indicate that elevated NR2F1 expression in tumor cells can induce dormancy in lung tissues by co-regulating with SMAD4 and TGFβ, causing tumor cells to exit the cell cycle." (PMID 39311119, 2024). "Although emerging evidence has revealed a key role for SMAD4 deficiency in driving PDAC, the molecular mechanisms underlying the contribution of SMAD4 loss to tumor malignancy in PDAC is less well defined." (PMID 38789418, 2024). "The few existing studies suggest that SMAD4 loss is associated with shorter survival, worse tumor regression scores (TRS), and metastatic progression under NAT." (PMID 37568581, 2023). "Mutation of genes encoding SMAD transcription factors (SMAD2, SMAD4) revokes TGF-β signaling’s tumor-suppressive effects and triggers OSCC progression." (PMID 37373414, 2023). "In DSS tumors, activin signaling genes (Acvr1b, Acvr2a, and Smad4) were highly mutated, suggesting the involvement of activin signaling in inflammation-associated tumor development." (PMID 37845228, 2023). "Loss of SMAD4/DPC4 tumour suppressive activity in PDAC leads to the acquisition of oncogenic function of SMAD2/3 and the associated deleterious effects." (PMID 37685308, 2023). "As an example, SVs can affect tumour suppressors, including SMAD4 and CDKN2A, by causing homozygous deletion or inactivating alterations." (PMID 36765737, 2023).
tumor (continued). "As many as 49.15% of PDACs presented SMAD4 nuclear loss of expression, defined as the nuclear expression of SMAD4 in <5% of tumor cells (see Section 2)." (PMID 37568581, 2023). "Although deletion of the SMAD4 gene is associated with tumor progression, metastasis, and poor prognosis, two other studies concluded that the mutation profiles of SMAD4 are highly concordant in primary CRC and CRLM." (PMID 38201487, 2023). "Expression of SMAD4 in tumor cytoplasm was correlated with weight loss and pathological stage, whereas SMAD4 in stromal cytoplasm was correlated with pathological stage only." (PMID 36900240, 2023). "RNA-Seq data confirm that both G1/S Phase- and G2/M Phase-associated genes are suppressed upon expression of SMAD4 within the tumor organoids." (PMID 38136364, 2023). "In the oncogenic BRAF-V600E mouse model, deletion of the tumour suppressor SMAD4 promoted rapid development and the progression of serrated tumours, and SMAD4 mutations co-occurred with BRAF-V600E mutations in human patient tumours." (PMID 37685308, 2023). "On the other hand, 30–35% of primary HNSCC tumours present SMAD4 loss of heterozygosity or high intratumoral heterogeneity, constituting a good candidate oncogene for these models." (PMID 36765175, 2023). "The TGFβ signaling mediator SMAD4 is a key tumor suppressor whose loss or mutation is involved in colorectal and pancreatic tumorigenesis." (PMID 37377893, 2023). "Free MTO was tested in for its efficacy to reduce the viability of cells and growth of tumor spheroids depending on their SMAD4 mutation status." (PMID 37049199, 2023). "Smad4 is a critical tumor suppressor found mutated in many late-stage cancers, yet the role of Smad4 in serrated cancer invasion is still relatively understudied." (PMID 38136364, 2023). "The tumor-suppressive function of SMAD4 has often been associated with the suppression of WNT and proliferation, particularly in the intestinal tract." (PMID 38136364, 2023). "(see Section 3), PanIN progression mechanisms involve mutations in tumor-suppressing genes that lead to the activation of TGFβ signaling pathways (SMAD4/TGFBR1/TGFBR2)." (PMID 35565450, 2022). "A substantial amount of evidence has already shown that the loss of the tumor suppressor SMAD4 correlates with metastasis occurrence and poor chemo–response in patients with CRC." (PMID 36497403, 2022). "Here, we review the function of SMAD4 inactivation in the context of a specific biological process called epithelial–mesenchymal transition, as it has been increasingly associated with tumor formation, metastasis and resistance to therapy." (PMID 35205719, 2022). "Our data suggest that Smad4-deficient T cells promote CAC through mechanisms that include an IFN-γ-dependent suppression of the tumor suppressor 15-PGDH." (PMID 36045676, 2022). "We have also developed and validated patient‐derived CRC tumoroid models for further investigation of the processes underlying tumor progression and resistance to therapy in association with SMAD4 loss." (PMID 34114372, 2022). "In 50–60% of JPs patients’ genomes, a germline mutation is found in SMAD4 or BMPR1A tumor suppressor genes involved in the BMP/TGF-β signaling pathway." (PMID 36553592, 2022).
tumor (continued). "For instance, the loss of Smad4 in tumor epithelial cells mutated in Apc enhances expression of the inflammatory chemokine CCL9 to promote malignant progression of the Apc mutant tumors by recruiting MMP-expressing CCR1+ bone marrow–derived cells." (PMID 36970719, 2022). "Studies have reported an association of SMAD4 genetic variation with tumor invasion, metastasis, and prognosis in various cancers." (PMID 36072013, 2022). "SMAD4 mutations and loss of SMAD4 protein have only been identified in the late phases of tumor development." (PMID 36358777, 2022). "Reduced SMAD4 expression is common in tumours and occurs through a combination of mutations, copy loss and transcriptional downregulation." (PMID 35144669, 2022). "These tumoroid models will facilitate investigation of the complex transcriptional mechanisms involved in the loss of tumor suppression in association with SMAD4 loss in ongoing studies." (PMID 34114372, 2022). "Accordingly, Smad4 deficiency promotes PDAC immunogenicity by inducing tumor‐intrinsic DNA damage‐elicited type I interferon signaling." (PMID 35064757, 2022). "Tumor suppressor gene SMAD4 is frequently mutated or silenced during tumor initiation and development." (PMID 35274815, 2022). "SMAD4 loss in animal models initiates tumour formation, promotes the progression of oncogene-initiated lesions, and stimulates the development of metastases." (PMID 35144669, 2022). "On the other hand, the loss of SMAD4, a transcription factor involved in the signaling of the TGF-β superfamily, promotes tumor progression and SMAD4-deficient CRC, and is linked to short survival for patients." (PMID 36230757, 2022). "The TGFβ signaling pathway and tumor suppressor SMAD4 mutations have been implicated in the serrated colon carcinogenesis pathway commonly resulting from BRAF mutations." (PMID 36295658, 2022). "For example, the loss of the tumor suppressor Smad4 in tumor epithelial cells mutated in Apc promotes the invasiveness of intestinal tumors through recruitment of matrix metalloproteinase (MMP)-expressing CCR1+ bone marrow–derived cells to the invasion front." (PMID 36970719, 2022). "Loss of Smad4 in PDAC tumor cells inhibited tumor growth in vivo in a manner dependent on CD8+ T cells and type I conventional dendritic cells (cDC1)." (PMID 35064757, 2022). "The initial APC and KRAS mutations drive effective proliferation and growth, while inactivation mutations in Smad4 prevent differentiation during tumor progression." (PMID 35273961, 2022). "Given that the relationship between SMAD4 was highly predictive for both PD-L1 expression and increased lymphocyte infiltration, we also evaluated the association between PD-L1 and tumor-infiltrating lymphocytes." (PMID 35155243, 2022).
tumor (continued). "In conclusion, this work reveals that SMAD4 inactivation in PDAC not only results in a loss of SMAD4 tumor suppressive function but is concomitant to the oncogenic gain-of-function of SMAD2 and SMAD3." (PMID 36207615, 2022). "To verify if tumor‐infiltrating T cells were responsible for Smad4 loss‐induced tumor suppression, we depleted T cells via intraperitoneal injection of anti‐CD8 or anti‐CD4 neutralizing antibodies prior to tumor cell inoculation." (PMID 35064757, 2022). "In PDAC, a loss of SMAD4 expression has been associated with tumor size, peripancreatic extension, TNM staging, lymphatic invasion, nodal involvement and poor differentiation, influencing OS and DFS." (PMID 35205719, 2022). "Further research indicated that the m6Ascore and tumor mutation burden were significantly correlated, and patients with low m6Ascore had higher mutation rates in SMAD4 and TTN." (PMID 35606813, 2022). "Overall, SMAD4 loss is associated with a more aggressive phenotype, attributed to tumor cells derived-EV transfer to myeloid cells, increasing their expansion and immunosuppressive activity, and favoring a pro-tumoral environment." (PMID 34207163, 2021). "Intriguingly, the authors did show that, at least in tumour cells, loss of SMAD4 expression correlated with reduced hydroxymethylation, implicating TGFβ signalling as an additional regulator of hydroxymethylation." (PMID 34638468, 2021). "Nuclear SMAD4 expression and tumor size were significant independent risk factors affecting the DSS of patients with ccRCC in multivariable Cox proportional analysis, with hazard ratios of 3.70 and 1.71 and P values 0.006 and 0.008, respectively." (PMID 34012911, 2021). "Patients with back mutations in K-Ras and SMAD4 showed higher infiltration of granzyme B+ (GrzB+) T cells in the metastatic tumor microenvironment." (PMID 34204435, 2021). "Tumor cells with a loss of SMAD4 display increased levels of reactive oxygen species (ROS) and radiation-induced autophagy, thereby limiting the tumoricidal effects of radiation in vivo." (PMID 34680235, 2021). "The results of the multivariable analysis showed that nucleolar grade, nuclear SMAD4 expression, tumor stage, and tumor size were significant risk factors affecting the DSS of patients with RCC." (PMID 34012911, 2021). "Somatic mutations of SMAD4 are associated with more aggressive tumor biology, poor response to chemotherapy, metastases, and unfavorable overall survival among patients with resectable and unresectable CRC37,38." (PMID 34599254, 2021). "Knockdown experiments suggested that SMAD4 was not necessary, but we subsequently showed that tumor cells deleted for SMAD4 or containing mutations in SMAD4 that abolish interactions with activated R-SMADs, abrogated TGF-β-induced degradation of SKI/SKIL." (PMID 33416497, 2021). "In agreement with this, loss-of-function mutations in Smad4 are common during late stages of CRC, especially with right-sided tumours, and loss of Smad4 has been linked with metastasis and worse prognosis." (PMID 34867090, 2021). "Single-cell analysis has been used to explore the relationship between immune cell infiltration and tumor progression in prostate adenocarcinoma GEMMs deficient for Pten and Smad4." (PMID 32929562, 2021). "Loss of SMAD4 allows tumor progression by upregulating autophagy, a cell survival mechanism that counteracts apoptosis and allows intracellular recycling of macromolecules." (PMID 34002944, 2021). "Combined OR suggested that SMAD4 gene mutation has nothing to do with age, gender, tumor grade, MSI or BRAF status." (PMID 34301194, 2021). "We have also found that long-term administration of Metformin significantly reduced tumor stage and improved survival in patients with SMAD4-deficient PDAC." (PMID 32737864, 2021).
tumor (continued). "It has been reported that CRC with loss of SMAD4 expression is associated with aggressive tumor behavior, poor prognosis and chemoresistance to 5-fluorouracil-based therapy, as well as decreased tumoral and peritumoral immune infiltration." (PMID 34381313, 2021). "Increased HNF4G are correlated with SMAD4 deficiency in PDAC tumor samples and associated with metastasis and poor survival time in xenograft animal model and in patients with PDAC (log-rank P = 0.036; HR = 1.60, 95% CI = 1.03–2.47)." (PMID 32737864, 2021). "For instance, Smad4 protein expression in a cytoplasmic fraction is gradually increased in association with tumor aggressiveness and progression, evaluated by tumor grade and myometrial infiltration." (PMID 34501347, 2021). "In a GEM (genetically engineered mouse) model for PDAC, it was shown that SMAD4 mutations can lead to increased tumor development." (PMID 34944807, 2021). "Epithelial depletion of the type 1 receptor promoted pancreatic tumourigenesis, in line with findings in Smad4 and Tgfbr2 deficient models, however, systemic depletion revealed important TGFβ-mediated control of the tumour microenvironment (TME)." (PMID 34638468, 2021). "This study displayed a twofold higher SMAD4 mutation rate in pancreatic body/tail cancers than pancreatic head cancers among early‐stage tumours (I‐II)." (PMID 33452856, 2021). "We have verified for the first time that HNF4G overexpression can be caused by the deficiency of SMAD4, a tumor suppressor gene that is frequently deleted or mutated in PDAC." (PMID 32737864, 2021). "A decreased expression of cytoplasmic SMAD4 (Q1-3 vs. Q4) was associated with advanced local tumor growth (T category), UICC stage, and MSI status." (PMID 34749812, 2021). "Smad4 is a tumour suppressor gene and its mutation or control indirectly disturbs the TGFβ signalling pathway." (PMID 34742256, 2021). "Another two tumor suppressors, SMAD4 and CDKN2A, had 53 mutations in 48 samples and 37 mutations in 35 samples, respectively." (PMID 34368001, 2021). "Our results indicated that nuclear SMAD4 expression and tumor size were independent significant risk factors affecting the DSS of patients with RCC and ccRCC as the most metastatic subtype in multivariable analysis." (PMID 34012911, 2021). "Tumor cells with a loss of SMAD4 displayed increased FOSL1 expression which is both necessary and sufficient to enhance the metastatic colonization of the lungs." (PMID 34680235, 2021). "SMAD2 and SMAD3 mRNA levels are associated with nuclear and FIGO grades, and the SMAD4 mRNA level is significantly associated with tumor size, tumor subtype, lymphovascular invasion, nuclear and FIGO grade, and disease-free survival." (PMID 34501347, 2021). "Additional more aggressive models have been created and combine Kras mutations with other genetic alterations, especially in tumor suppressor genes, for instance Ink4a/Arf and Smad4, to accelerate tumor formation and progression." (PMID 33503832, 2021). "Higher SMAD4 promoter methylation is significantly associated with high tumor grade, recurrence, metastasis, and elevated AFP (p < 0.01)." (PMID 34571856, 2021). "SMAD4 inactivation is a late event, detected only in PanIN-3 lesions and invasive tumors, so it is considered to be linked with tumor progression and worse prognosis." (PMID 33669845, 2021). "For 13 stroma-specific mutations, there were only two driver events (15.4%, KRAS G12V for P05, SMAD4 W302* for P43), while 57 driver events (42.5%) were underlined in 134 neoplasm-specific mutations." (PMID 34733795, 2021). "In many cancers, mutation or low expression of Smad4 switches its function from tumor inhibition to tumor promotion." (PMID 33322272, 2020).